MYL11 (myosin light chain 11)
Description:
Myosin regulatory subunit that plays an essential role to maintain muscle integrity during early development (By similarity). Plays a role in muscle contraction (By similarity).
Synonyms: MYLPF; MRLC2; HUMMLC2B; DA1C; MLC2B
Tractability: No criterion of Open Targets' tractability assessment is met for any kind of drug.
Gene: Protein-coding gene on chromosome 16 (30,370,332 to 30,377,991, forward strand). Ensembl gene ENSG00000180209.
Pathways (Reactome):
Muscle contraction: Smooth Muscle Contraction
Gene Ontology:
Molecular function: protein binding; calcium ion binding; structural constituent of muscle
Biological process: muscle contraction; actin-myosin filament sliding; muscle tissue morphogenesis; skeletal muscle tissue development
Cellular component: lysosomal membrane; cytoplasm; cytosol; muscle myosin complex
Genetic constraint (gnomAD): Loss-of-function variants: 10 observed, 24.24 expected, observed/expected ratio (o/e) 0.41, 90% interval 0.25 to 0.7. The upper end of that interval is the gene's LOEUF score, 0.7, which puts it in group 2 of 6, group 1 being the genes least tolerant of losing a copy. Missense variants: 209 observed, 236.67 expected, observed/expected ratio (o/e) 0.88, 90% interval 0.79 to 0.99. Synonymous variants: 74 observed, 86.77 expected, observed/expected ratio (o/e) 0.85, 90% interval 0.71 to 1.03.
Homologues: Orthologues: chimpanzee MYL11 (100% identical), macaque MYL11 (98% identical), mouse Mylpf (96% identical), dog MYL11 (96% identical), guinea pig MYL11 (96% identical), rat Myl11 (96% identical), tropical clawed frog myl11 (83% identical), zebrafish mylpfb (82% identical), zebrafish mylpfa (81% identical), rabbit MYL11 (78% identical), pig MYL11 (70% identical), Caenorhabditis elegans mlc-1 (49% identical), and 1 more. Paralogues in human: MYL10 (73% identical), MYL2 (71% identical), MYL5 (59% identical), MYL7 (58% identical), MYL12A (56% identical), MYL12B (56% identical), MYL9 (56% identical).
Diseases named in the same sentence as MYL11 in open-access papers:
MYL11 is named in the same sentence as 9 diseases in open-access papers, as found by Europe PMC text mining. Sharing a sentence is not in itself a finding about the gene and the disease.
MYL11 shares sentences with these, for which no sentence is quoted: aortic coarctation (1 paper); breast carcinoma (1); cancer (1); chronic heart failure (1); infection (1); myocardial infarction (1); myopathies (1); Obesity (1); tongue tumor (1).